MX1 (MX dynamin like GTPase 1)
Diseases named in the same sentence as MX1 in open-access papers (continued):
Sharing a sentence is not in itself a finding about the gene and the disease.
infection (continued). "ZIKV infection in primary Tupaia cells induced an upregulation of cytokine mRNA levels over the infection time, including those of IL-6, IL-8, TNF-α, IFN-β, CXCL9, and MX1, where IL-6, IL-8, and TNF-α mRNA levels were significantly elevated 6 h post-infection." (PMID 31842286, 2019). "As expected, HSV-1 ICP0-null mutant infection efficiently induced the transcription (by 8–9 hpi) and expression (by 16 hpi) of three independent ISG products (Mx1, ISG15, and ISG54), a host response that was significantly impaired during WT HSV-1 infection." (PMID 29309427, 2018). "Cortical neurons induce type I IFN after infection, respond to IFN treatment, and upregulate viperin and other ISGs (Mx1 and Ifit1)." (PMID 29544502, 2018). "Correspondingly, qRT-PCR demonstrated that the induction of ISGs (Mx1, ISG15, ISG54) was significantly impaired in both IFI16 or PML depleted cells in response to HSV-1 ICP0-null mutant infection at 9 hpi." (PMID 29309427, 2018). "Surprisingly, qRT-PCR analysis demonstrated that only HFt cells induced ISG (Mx1, ISG15, ISG54) expression during HSV-1 ICP0-null mutant infection." (PMID 29309427, 2018). "RIG-I and MAVS overexpression resulted in marked increase of Mx1 and GBP-1 at both 12 and 24 hours post-infection when compared to H5N1-infected control cells." (PMID 28418930, 2017). "Overexpression of SOCS1 in chIFN-α-stimulated DF-1 led to a relative decrease in expression of interferon-stimulated genes (ISGs; MX1 and IFIT5) and increased viral yield in response to PBG98 infection." (PMID 29235573, 2017). "After prolonged HEV gt3 infection for more than 3 months, significantly lower expression levels of STAT1, RSAD2 and MX1 compared to uninfected controls were observed, suggesting possible viral interference with the host’s cell innate immune signaling." (PMID 28811492, 2017). "Mx1 and Ifit1 mRNA expression increased in MLN on days 2 to 5 after infection, compared to controls." (PMID 27405244, 2016). "Novel truncated proteoforms of MX1 were identified in infected cells and phosphorylation driven regulation of HSPB1 proteoforms was correlated with infection." (PMID 27451424, 2016). "YFP+B220+ B cells were contrastingly uncommon in naive Mx1-cre x ROSA26-YFP mice and increased >5-fold by infection." (PMID 27223694, 2016). "This large up-regulation in Mx1 (spleen 220-fold, lung 60-fold) suggested that the IFNs were active in inducing IFN-stimulated genes during Lao/14 infection." (PMID 27631618, 2016). "Investigating the predictive potential of RNA levels at 2 weeks post infection (wpi) revealed that FAM26F, MX1 and CXCL10 were predictive of chronic phase set-point viral load only when peak viraemia correlated with the further course of infection." (PMID 27902344, 2016). "Induction of the ISG protein myxovirus resistance protein 1 (Mx1, also known as MxA), a key biomarker of the innate response against HCV, was assessed in iHLCs following infection with HCVcc." (PMID 25826356, 2015). "H5N1 infection in DF-1 cells induced higher levels of Mx1 and OASL gene expression than H9N2 infection at 15 hpi (p value <0.01)." (PMID 25557928, 2015). "Mx1 has been shown to be upregulated in swine PBMCs of pigs infected with replication defective Ad5 expressing IFN-α at one and two days post-infection." (PMID 26193305, 2015). "In order to determine more precisely the kinetics upon infection, BST2 and MX1 transcription were assessed during the 1st weeks of infection in seven animals infected with different doses of SIVmac 251MPBMC as part of an in vivo titration study." (PMID 26554913, 2015). "Antiviral genes, including IFNA, IFNG, MX1, IFITM1, IFITM3, and IFITM5, were upregulated in response to infection." (PMID 25505077, 2015). "Differences in virus loads and ability to induce cytopathic effect, inhibition of protein synthesis, apoptosis, and induction of IFNa, Mx1, PKR or TNFα gene expression at different times post infection were examined." (PMID 26263557, 2015).
infection (continued). "In BEAS-2B cells at 10 h of infection, IRF-7, ISG15 and Mx1 expression were significantly down-regulated (p<0.05) while STING expression was significantly up-regulated (p<0.05); expression of IFN-β and IL-6 was unchanged." (PMID 25313647, 2014). "In the present study, the IFN-stimulated genes (IFIT1, IFIT3, MX1, ISG15, OAS1, and IFI6) were dramatically increased at 16 h and 24 h post infection, which should trigger powerful antiviral functions." (PMID 23527143, 2013). "While it is unlikely a direct transcriptional regulator, Mx1's potent ability to inhibit IAV replication likely alters the signaling environments and host response pathways triggered in response to infection." (PMID 23468633, 2013). "Genes that were induced during the first 2 days after infection included early stress response genes (early growth response, Fos, Jun) and IFN responsive genes (MX1 and 2, STAT-1, IFN-γ inducible protein-10, guanylate binding protein-1 and -2)." (PMID 17725815, 2007). "P-STAT1, STAT1, and MX1 levels were similar across all siMETTL3 groups (Mock, VSV-ΔM51, VSV-Mwt, and VSV-Mwt-P1), with no further increase in P-STAT1, STAT1, or MX1 was observed after infection with any virus, compared to mock." (PMID 40214229, 2025). "Thus, the expression levels of DDX58, DHX58, IFIH1, MX1, and OAS2 decreased slightly as infection with 26544/OG10 progressed (higher fold-changes at 3 hpi compared to 21 hpi)." (PMID 40530033, 2025). "In the brain, infection with Bov342 induced the expression of type-I (Ifna5, Ifnb), -II (Ifng), and -III (Ifnl2) interferons (IFN), interferon stimulated genes (ISGs) (Isg15, Ifit1, Mx1, Oas1), and pro-inflammatory cytokines (Il1b, Il6, and Tnfa) at endpoint." (PMID 40410375, 2025). "We found a significant temporal induction of ISGs (for example, MX1, RTP4, IRF7, USP18, TRANK1) in alvORG at day 3 after infection compared to mock-infected samples or nasalALI at day 5 and day 7 compared to day 1 after infection." (PMID 40399606, 2025). "These cells showed the expected increase in IFNλ1 and MX1 mRNA levels under both infection conditions and no change in IFNλ1 mRNA levels upon IFNα-2a treatment." (PMID 40434103, 2025). "All three selected ISGs namely Mx1, IFIT3 and ISG15 were induced after infection with BADwt." (PMID 40143353, 2025). "At 24 h post-infection, HMPV boosted ISG15, OAS1, MX1, and IRF7 by multiples of ten magnitudes." (PMID 40732740, 2025). "IFNλ1 and MX1 levels were downregulated upon IFNα-2a treatment compared to mock conditions, and only a slight increase in IFNλ1 and no change in MX1 expression were observed upon infection with the wild-type virus." (PMID 40434103, 2025). "Finally, at 72 hours post-PIV3 infection, the transcriptional response remains interferon-centric, with continued expression of IFIT1, IFIT2, IFIT3, MX1, and OAS2." (PMID 39591472, 2024). "Infection with DTMUV strongly increased the expression of a set of type I IFN genes and key ISGs (Mx1, OAS1, IFITM3, and OASL) through activation of the molecular adaptors MDA5 and TLR-3 involved in the RLR and TLR pathways, respectively, leading to decreased viral replication." (PMID 38793692, 2024). "Inhibition of HIV-1WT infection by chimeric MX1 expressing the N-terminal 91 amino acids of MX2 (MX1MX2-NTD) was reversed by CsA treatment in both HeLa and HT1080 cells (even enhancing HIV-1WT infection in CsA-treated HT1080 cells to a greater degree than MX2)." (PMID 38512975, 2024). "To determine if CPSF6 knock-out could be altering the innate immune response to infection, we assessed expression of a representative ISG, MX1, in primary CD4+ T cells from the four independent donors above at 5 days post-infection." (PMID 39678349, 2024). "MX1 gene expression correlates with a rapid and transient wave of ISG expression across all cell types, which may precede PCR detection of replicative infection." (PMID 39616162, 2024).
infection (continued). "This difference was less evident in data from convalescent patients, and consistent with transient cell-type specific opening of the IFI27 locus in established infection, providing a mechanistic basis for the temporal delay and cellular restriction of IFI27 responses compared to MX1." (PMID 39616162, 2024). "Furthermore, only infection with Omicron resulted in a significant induction of Ifna5 and Ifnb, ISG-driven antiviral effectors Mx1, Oas1, and Viperin, and pro-inflammatory mediators Cxcl10 and Il6." (PMID 38742107, 2024). "While HTNV-infected cells increased expression of the ISGs RIG-I, MDA5, and Mx1/2/3 over the course of the six-day infection, SEOV did not drive increased ISG protein production." (PMID 39585900, 2024). "Finally, at 72 hours post-PIV3 infection, the transcriptional response remains robust and interferon-centric, with continued expression of IFIT1, IFIT2, IFIT3, MX1, and OAS2." (PMID 39591472, 2024). "Early acute infection and A549 infected cells shared 150 upregulated genes including ATF3, a stress induced transcription factor, as well as other genes involved in the innate immune response such as MX1, DDX58/RIG-I, IFIT1, IFIT2, DHX58/MDA5, and OASL." (PMID 39065267, 2024). "Furthermore, the levels of OAS1, MX1, and ZAP expression in the prestimulated and post stimulated IPEC-J2 cells were found to be significantly different following L. mucosae G01 infection (p < 0.05)." (PMID 39171258, 2024). "Several ISGs, including MX1, MX2, and OAS1, were upregulated in 170-infected animals at many different time points but were generally only significantly upregulated in CL8 animals at weeks 1 and 2 post-infection." (PMID 38317183, 2024). "By contrast, the overexpression of Ythdc2 could significantly inhibit the expression levels of interferon IFN1, TNF-α, Mx1, ISG15, and Viperin after SCRV infection." (PMID 38361078, 2024). "Seven differentially expressed genes (DDX58, STAT1, MX1, IRAK1, MAPK11, RELA, and ICAM1) were randomly selected and quantified using qRT-PCR to validate the differential expression observed in A549 cells using RNA-Seq across varying infection time points." (PMID 38673764, 2024). "Indeed, we found that the baseline protein expression levels of cytosolic pattern recognition receptor (PRR) RIG-I, as well as ISGs (MX1 and IFITM1), were significantly elevated prior to secondary infection." (PMID 37190061, 2023). "Furthermore, the temporal expression profiles of eight selected antiviral-related mRNA including IRF3, IRF7, IKKβ, TBK1, IFIT1, IFI44, MX1 and ISG15 were detected by qRT-PCR, which showed a significantly stronger response at early infection under 20 °C." (PMID 37627029, 2023). "SARS-CoV-2-Δ8 infection showed a trend of increasing IFN signaling (IFNλ3, interferon-stimulated gene [ISG15], and MX1, P values 0.4337, 0.1126, and 0.2285, respectively) as compared to WT at 3 dpi, while reducing IFN-stimulated gene levels (IFNλ3, ISG15, IFIT1, OAS1, and XAF1) at 6 dpi." (PMID 37623322, 2023). "Furthermore, the ISGs Mx1, RSAD2, and IFITM1 were upregulated early after infection with IAV DIPs compared to infections with YFV or RSV only." (PMID 37766278, 2023). "We observed a NS1 dosage-dependent host response for genes involved in the inflammatory response (IL-6, IFNB1) and interferon stimulation (IFIT1, MX1, ISG15), with the IAV-NS1-T infection generating an intermediate phenotype at both the transcript and at the protein levels." (PMID 37876781, 2023). "Upon SCRV infection, MORC3 could significantly inhibit the expression levels of ISG15, Mx1, Viperin, and IFN1." (PMID 38150467, 2023). "Only 2 of the 12 up-regulated ISGs (CXCL10 and IFI16) and 2 of the 4 down-regulated (CLDN2 and MX1) were common between HEV-3c and HEV-3f infection, suggesting that the IFN response might differ depending on the HEV subtype involved in infected swine." (PMID 38058490, 2023).
infection (continued). "We further assessed the impact of VHSV Ia infection on IFN signaling by monitoring the effect of infection on the MX1, expression with and without exogenous IFN treatment." (PMID 36851680, 2023). "Upon SCRV infection, the overexpression of Linear-Flag-MORC3-84aa expression plasmids could significantly inhibit the expression levels of ISG15, Mx1 and Viperin." (PMID 38150467, 2023). "Besides, upon F48E9 infection, 9-butyl-harmol treatment increased the expression of OASL and MX1 to 2.51- and 3.13-fold, respectively." (PMID 36877059, 2023). "Interestingly, however, the protein expression levels of MX1 and IFITM1 during secondary H3N2 infection and HRV-A16 re-infection were significantly increased as compared to their respective single infections." (PMID 37190061, 2023). "At the timepoint of 5 h pi, a time when secondary infections are excluded, the experiment does not inform about a possible effect of Mx1 on the replication, assembly, and/or budding of new viral particles." (PMID 37243140, 2023). "However, the results showed that knockdown of MORC3 can significantly enhance the expression levels of ISG15, Mx1, Viperin, and IFN1 upon SCRV infection." (PMID 38150467, 2023). "Interestingly, unlike the WT rotavirus, the NSP1 mutant rotavirus led to an induction of Mx1-mCherry in the IFNLR1−/− pMx1-mCherry cells at late time points, indicating that type I IFNs were secreted following infection (bottom)." (PMID 36000839, 2022). "Upon Tha and Th2P-4M infection, foetal pAstrocytes strongly induced the expression of IFIH1, CCL5, and CXCL10, whereas hiMicros strongly upregulated expression of CXCL10 and genes coding for antiviral proteins ISG15 and MX1." (PMID 36680128, 2022). "Overexpression of IRF7 in KO IFNAR1 cells infected with DTMUV partially restored the expression of IFN-β at 12–48 hpi, IFIT5 at 36–48 hpi, IRF1 at 48 hpi, and MX1 at 12–48 hpi, indicating a type I IFN-independent role of IRF7 in the induction of these genes during DTMUV infection." (PMID 35891486, 2022). "In this study, IRF7 and MX1 were upregulated in coinfected cells, which indicated that MDV and REV coinfection in CEF cells leads to pronounced induction of innate immune responses in comparison to a single infection." (PMID 35392111, 2022). "Similarly, inhibiting the expression of miR-126-5p infection with NDV significantly promoted the expression of IFNβ, PKR, MX1, IL-1β, IL-6, and IL-8." (PMID 36224663, 2022). "Notably, multiple antiviral proteins were also dramatically decreased in PAMs during the PRRSV-ADE infection, including ISG15, ISG20, IFIT1 (ISG56), IFIT2 (ISG54), IFIT3 (ISG60), IFIT5 (ISG58), OAS1, Mx1, RSAD2, TRIM22, TRIM25 and TRIM34, except for TRIM52." (PMID 36680075, 2022). "Based on the role in transcriptional and translational interference, MX1 and MX2 upregulation by pOECs could aim to limit Ct propagation and thereby Ct infection within the genital tract." (PMID 34684219, 2021). "The overexpression of circDtx1 could significantly inhibit the expression levels of interferon IFN1, inflammatory cytokines (TNF-α), and antiviral genes such as myxovirus resistance protein 1 (MX1) and ISG15 after SCRV infection." (PMID 33735323, 2021). "The study is nevertheless limited in its relatively small sample size, assessment of RIG-1, MDA5, ISG-15, and MX1, which was performed in tissue culture, and lack of disease severity assessment after infection." (PMID 34836388, 2021). "Increasing MX1 levels also corresponded with the detection of secreted IFN-β in the supernatant, as measured by ELISA, which increased steadily up to 72 h and then remained elevated up to 120 h post-infection." (PMID 34079533, 2021). "These ISGs, which include MX1, MX2 and BST2, were found to be upregulated in hPIV1-infected cells by at least 7-fold compared to hPIV3 infected cells at both early and late time points after infection." (PMID 34529742, 2021).
infection (continued). "Furthermore, a dampened induction of several downstream ISGs, including MX1, OAS1, ISG-15, and viperin was observed on day 4 post-infection." (PMID 33653328, 2021). "While these pro-inflammatory cytokines were not increased, Ct infection of pOECs did lead to a significant increase in the mRNA expression of the interferon regulated genes MX1, MX2, and CMPK2." (PMID 34684219, 2021). "To investigate whether MX1 and IFIT1 actively antagonize ZIKV propagation in SC, we next transfected SC with either MX1 or IFIT1 siRNA 24 h prior to infection (MOI 1)." (PMID 34079533, 2021). "Moreover, the results showed that IFN1, TNF-α, MX1, and ISG15 were significantly decreased by the introduction of miR-15a-5p mimics upon SCRV infection." (PMID 33735323, 2021). "However, the interferon response (IFNβ1, CXCL10, ISG15, MX1 and MX2) was delayed and increased at 48 h post-infection." (PMID 34452468, 2021). "Infection with ΔNS1 virus but not WT viruses yielded detectable levels of Mx1-specific mRNA levels in lungs 24 h post infection." (PMID 34773048, 2021). "However, concomitant with the higher gene expression observed, Mx1 and ISG15 reach higher protein levels in A549/PKR KO cells than in A549/Scr control cells at late times after infection." (PMID 34372519, 2021). "Our results are consistent with the hypothesis that restriction factors such as IRF1, MX1, STAT1, C18orf25 limit lytic infection." (PMID 33914843, 2021). "After the first experimental infection, the mRNA transcription levels of perforin, granzyme B, INF-γ, and antiviral factor MX1 and the number of IFN-γ-releasing PBMCs when stimulated with the first challenge virus were higher in vaccinated cats compared to control cats." (PMID 34578316, 2021). "Infection with either HO or KY alone had similar inhibitory effects on most ISGs (ISG15, GBP4, HERC5, RSAD2, DDX58, and IFIT3), although a slightly greater inhibitory effect of HO was observed on IFI27 and MX1." (PMID 33898551, 2021). "In parallel, infections were performed in BALB/c mice which have a non-functional Mx1 gene due to a large frameshift deletion." (PMID 34401874, 2021). "In addition, Calu-3 cells increased their expression of Mx1 and OAS1 at hours 48 and 72 post-infection." (PMID 34578229, 2021). "Upon infection of these cells with ZIKV for 24 and 48 h, we observed a decreased antiviral response, as evidenced by significantly lower mRNA levels of IFN-β and the ISGs IFIT1 and Mx1." (PMID 33658344, 2021). "Infection with ΔNS1 virus but not WT viruses yielded detectable levels of Mx1-specific mRNA levels in lungs 24 hours post infection." (PMID 34401874, 2021). "In miiuy croaker brain cells (MBrC), MAVS-specific siRNA could also significantly suppress the expression of IFN-2, TNF-α, Mx1, and ISG15 upon SCRV infection." (PMID 32678830, 2020). "Our main findings were: 1) the host immune response was initiated only in fetuses with detectable levels of PRRSV; 2) upon infection of fetal thymus, a set of core responsive IFN-inducible genes (CXCL10, IFIH1, IFIT1, IFIT3, ISG15, and MX1) were strongly upregulated in both tissues." (PMID 33148169, 2020). "Only Mx1 showed a significant increase in WT and TLR3 KO DF-1 cells after AIV infection." (PMID 32425931, 2020). "As expected, rWT VHSV IVb infection alone induced the MX1 promoter 20-fold more than VHSV lacking IVb NV protein (VHSV-ΔNV)." (PMID 32365817, 2020). "MX1 was the most overexpressed gene in the Rosa 1 [2x] group, and its overexpression was also reported in CEF cells and chickens infected with H5N1 or H5N2 viruses and in the lungs of chickens infected with H5N1 virus from 24 h post infection." (PMID 32381003, 2020). "In MBrC cells, knockdown of MARL could also significantly inhibit the expression of IFN-2, TNF-α, Mx1, and ISG15 upon SCRV infection." (PMID 32678830, 2020).